GRIK2 (glutamate ionotropic receptor kainate type subunit 2)
Diseases named in the same sentence as GRIK2 in open-access papers (continued):
Sharing a sentence is not in itself a finding about the gene and the disease.
lung carcinoma (3 papers, 2013 to 2021). "Of the 30 common Significant DNA methylated genes across Stages II and III, GRIK2 and NEUROG1 have been previously reported being DNA methylated biomarker for lung squamous cell carcinoma, and a Stage I biomarker in lung cancer respectively." (PMID 24369052, 2013).
lymphoid leukemia (3 papers, 2022 to 2024). A malignant lymphocytic neoplasm of B-cell or T-cell lineage involving primarily the bone marrow and the peripheral blood. "The deletion of the long arm of chromosome 6 in ALL patients typically occurs in the region of the GRIK2 gene most often affected by 6q16 deletions; complete or partial loss of GRIK2 function may contribute to some of the lymphoid leukemia proliferations." (PMID 39767649, 2024).
Obesity (3 papers, 2011 to 2022). Accumulation of substantial excess body fat. "The identified CpGs have the potential to improve our understanding of the underlying biological pathways in the connection between obesity and lung function, with 2 CpGs (cg19088553 on gene GRIK2 and cg00612625 on gene HPSE2) having the potential for causal association with lung function." (PMID 35906571, 2022). "From the GWAS, the significant markers associated with obesity-related traits including body weight (CACNA1B, C22orf39, U6, MYH14, PTPN2, SEH1L) and blood sugar (PRSS55, GRIK2), were identified." (PMID 33182249, 2020).
Alzheimer disease (2 papers, 2021 to 2022). A progressive, neurodegenerative disease characterized by loss of function and death of nerve cells in several areas of the brain leading to loss of cognitive function such as memory and language. "Gene-based analyses implicated AGXT2 and CALN1 for VL, while analyses of protein-protein interactions implicated synaptic proteins previously associated with Alzheimer disease biology, SYT9 and NRXN1 for VSTM; ZFAND5, GRIK2, and ZC3H18 for VL; and PRLHR for paragraph recall." (PMID 35974141, 2022).
bladder cancer (2 papers, 2025). "A GRIK2 peptide-specific cytotoxic T lymphocyte (CTL) clone was able to recognize GRIK2-overexpressing UM-UC-3 cells and ALDH-high clone cells, suggesting that GRIK2 peptides could serve as novel immunotherapeutic targets for bladder cancer CSCs/CICs." (PMID 40635786, 2025).
Chronic Fatigue Syndrome (2 papers, 2016 to 2019). "GRIK2 was proposed as a candidate biomarker in Chronic Fatigue Syndrome (CFS) after it was detected in the peripheral blood of CFS patients as differentially expressed." (PMID 27476530, 2016).
ischemia (2 papers, 2014 to 2025). A hypoperfusion of the BLOOD through an organ or tissue caused by a PATHOLOGIC CONSTRICTION or obstruction of its BLOOD VESSELS, or an absence of BLOOD CIRCULATION. "GRIK2 encodes a subunit of kainate-type glutamate receptors and has been implicated in excitotoxicity, a process in which excessive glutamate release during ischemia causes harmful calcium influx, leading to neuronal injury and death." (PMID 41342963, 2025).
lymph node metastasis (2 papers, 2017 to 2019). "GRIK2-positive cases showed a higher rate of lymph node metastasis (13%, P = 0.047), high grade of tumor (86%, P = 0.0002) and lymphovascular invasion (37%, P = 0.009) compared with GRIK2-negative cases." (PMID 28418868, 2017).
urinary tract carcinomas (2 papers, 2017 to 2025). "We furthermore analyzed the functions of GRIK2 by gene knockdown using siRNAs and gene overexpression, and analyzed the clinical significance of GRIK2 protein expression in urothelial carcinomas." (PMID 28418868, 2017). "GRIK2 maintains the function of urothelial carcinoma stem-like cells." (PMID 40709170, 2025). "Immunohistochemical staining revealed that higher levels of GRIK2 and ALDH1 expression were related to poorer prognosis in urinary tract carcinoma cases." (PMID 28418868, 2017). "The findings indicate that GRIK2 has a role in the maintenance of urothelial CSCs/CICs and that GRIK2 and ALDH1 can be prognosis prediction markers for urinary tract carcinomas." (PMID 28418868, 2017). "In this study, we successfully isolated urothelial carcinoma CSCs/CICs using the UC cell line UM-UC3 based on the ALDH1 activity assay and identified the glutamate receptor, ionotropic, kainate 2 (GRIK2) gene as a gene involved in the invasion ability of ALDH1 high activity cells." (PMID 28418868, 2017).
Arrhythmia (1 paper, 2025). Any cardiac rhythm other than the normal sinus rhythm. "However, research specifically focusing on the relationship between GRIK2 and arrhythmias or AF remains limited." (PMID 40894480, 2025).
atherosclerosis (1 paper, 2022). A disease characterized by the build-up of fatty material and calcium deposition in the arterial wall resulting in partial or complete occlusion of the arterial lumen. "Until now, few studies have reported the association between GRIK2 and atherosclerosis." (PMID 36159969, 2022).
autosomal recessive intellectual disability (1 paper, 2022). "It contains three genes GRM5, GRIK2, and GRIA4, and GluR6 is encoded by GRIK2 which is highly expressed in the brain and is associated with autosomal recessive intellectual disability." (PMID 36699455, 2022).
autosomal recessive mental retardation (1 paper, 2020). "GRIK2 encodes for GluR6, a kainite receptor that is highly expressed in the brain and is associated with autosomal recessive mental retardation." (PMID 32083286, 2020).
glioma (1 paper, 2021). A benign or malignant brain and spinal cord tumor that arises from glial cells (astrocytes, oligodendrocytes, ependymal cells). "From the Human Protein Atlas database, immunohistochemistry results showed that GRID2 and GRIK2 were up-regulated in gliomas than normal brain tissue." (PMID 33969375, 2021).
kidney stone (1 paper, 2023). "However, the functional role of Grik2 in the proximal tubular cells and kidney stone related PTs injury remains unclear." (PMID 37208718, 2023).
liver disease (1 paper, 2025). "Interestingly, many of the genes linked to the differentially methylated CpGs have been associated with liver disease progression (eg, DCP2, TRPV3, ARRB1, KCNIP4, MIR10A) and cancer formation or progression (eg, MTHFR, GRIK2, GSN, HOX3, KCNMA1)." (PMID 40275933, 2025).
migraine (1 paper, 2023). "GRIK2 rs2227283 was associated with migraine in the edge of significance [ORadj (95% CI) = 1.36 (0.99–1.89), p = 0.062]." (PMID 37303955, 2023). "GRIK2 rs2227283 was associated with migraine risk in unmatched data and associated with MA risk in matched data." (PMID 37303955, 2023). "In this case control study, the GRIK2 rs2227283 was the first time studied and found to be associated with migraine risk in the edge of significance." (PMID 37303955, 2023). "Differently, the associations of TRPV1 rs8065080 and GRIK2 rs2227283 with migraine were not significant due to the small sample size in matched data." (PMID 37303955, 2023). "Associations between the GRIK2, TRPV1, TRPV3 and TRPM8 gene polymorphisms and the risk of migraine." (PMID 37303955, 2023). "And GRIK2 rs2227283 was associated with MA rather than migraine." (PMID 37303955, 2023).
myopia (1 paper, 2018). "Glutamate receptor signaling was found to be involved in myopia development by two genetic linkage studies and also in a study of a glutamate receptor Grik2 mouse knockout model." (PMID 30300342, 2018).
nicotine dependence (1 paper, 2014). Physical and psychological dependence on nicotine. "The empirical data applications to nicotine dependence also identified two genes, GRIK2 and CSMD1, joint associated with the progression of nicotine dependence." (PMID 24986733, 2014). "In the initial dataset, two SNPs, rs6570989 and rs2930357, located in genes GRIK2 and CSMD1, are found to be significantly associated with the progression of nicotine dependence (ND)." (PMID 24986733, 2014).
oral cancer (1 paper, 2017). "Recently, polymorohism of GRIK2 TT (rs1335022) was associated with oral cancer." (PMID 28418868, 2017). "Recently, polymorohism of GRIK2 TT (rs1335022) was associated with high risk of oral cancer in tobacco habitués, indicating that GRIK2 might be related to carcinogenesis." (PMID 28418868, 2017).
osteosarcoma (1 paper, 2021). A usually aggressive malignant bone-forming mesenchymal neoplasm, predominantly affecting adolescents and young adults. "Deletions of the 6q16.3 region of their tumor-suppressor Glutamate Ionotropic Receptor Kainate Type Subunit 2 (GRIK2) gene in osteosarcomas have been shown to interfere with SETDB1 binding since this deleted region contains a SETDB1 binding site." (PMID 34440561, 2021). "This deletion, therefore, results in overexpression of the anti-oncogenic GRIK2, apoptosis and decreased proliferation and migration while also revealing a possible tumorigenic role of SETDB1 in osteosarcomas." (PMID 34440561, 2021).
pulmonary diseases (1 paper, 2022). "Although we were not able to assess the biological functionality of these CpGs due to the lack of expression data of their mapped genes (GRIK2 and HPSE2) in whole blood, earlier studies have linked both genes with pulmonary diseases." (PMID 35906571, 2022).
Sepsis (1 paper, 2024). Sepsis is defined as life-threatening organ dysfunction caused by a dysregulated host response to infection. "A missense site p.M620V in Grik2 and a 3′UTR site in Gria2 showed differential editing during sepsis." (PMID 39135964, 2024).
tumor (19 papers, 2012 to 2025). "GRIK2 encodes a glutamate receptor with tumor suppressor features." (PMID 37369946, 2023). "Furthermore, GRIK2 expression in UC tissues was associated with pathological N stage, tumor grade and lymphovascular invasion." (PMID 28418868, 2017). "Consequently, lack of TRMT11 may produce less efficient and unstable translation due to tRNA defects, or protein translation repression; plus the loss of GRIK2 tumor suppressor activity." (PMID 37369946, 2023). "In the tumor cells at metastatic locations, we detected meta-program IV (MAP2, GRIK2), a hallmark of neuron development, and meta-program I, the mesenchymal-neuroblast-like (MES-Nbt) state, which was enriched for genes related to the EMT such as ZEB1, ZEB2, and TEAD1." (PMID 41279557, 2025). "Interestingly, TRMT11 gene fusion with GRIK2 (TRMT11-GRIK2) has been identified as a frequent event in several tumor types, including primary and lymph node metastatic cancer from breast, colon, and ovary." (PMID 37369946, 2023). "In conclusion, our results demonstrate differential expression of GluR6/GRIK2 transcript variants in neuronal and non-neuronal tumor cells." (PMID 35328043, 2022). "These three methylation sites could regulate the expression of corresponding genes (RUNDC3A, GRIK2, and KIF26B) that cause tumor growth and development, and therefore these sites might become new targets for tumor treatment." (PMID 35669882, 2022). "A more dramatic loss of function is identified in the TRMT11-GRIK2 gene fusion; the TRMT11-GRIK2 gene fusion eliminates the open-reading frame of GRIK2, which is a potential tumor suppressor, and produces a large truncation of TRMT11, which is a tRNA methyltransferase." (PMID 31164957, 2019). "The protein expression of FCRL1, GRIK2, MAPK12, and OR51B5 showed differential level between normal colon tissue and tumor tissue." (PMID 38144182, 2023). "BEX1, PTGDS, GRIK2 and WFDC1, also in the top 10 downregulated probesets, have all been identified as downregulated in tumours or as inhibitors of cell proliferation in immortalised cell lines." (PMID 24148222, 2013). "Among them, BNC2, SYNM, and TCF21 target genes were detected in all tumor locations, and three targets (GRIK2, KLHL14, and MS4A2) were shared by R-CRC and L-CRC but not by RC." (PMID 37987361, 2023).
cancer (18 papers, 2014 to 2025). A tumor composed of atypical neoplastic, often pleomorphic cells that invade other tissues. "The deletion of TRMT11 reduces the stability of tRNA and may therefore adversely impact the protein translation of cancer cells, while the loss of GRIK2 may promote the growth of cancer cells." (PMID 31164957, 2019). "There have been a few reports in which the association between GRIK2 and cancers was described." (PMID 28418868, 2017). "Previous studies indicated that Grik2 played a role in the maintenance of cancer stem cells by promoting sphere-forming ability, invasion ability, and tumorigenicity, and governed the cell proliferation of normal human fibroblasts." (PMID 37208718, 2023). "Human TRMT11 is involved in carcinogenesis as part of a fusion gene with GRIK2, which is found in many cancer types." (PMID 34948388, 2021). "Moreover, editing events of these genes have been associated with cancer progression (e.g., AZIN1, COPA, CCNI, and FLNB) or neurological disorders (e.g., GRIK2 and GRIA2–4)." (PMID 35406793, 2022). "The 3-year cancer-specific survival rates of patients with GRIK2-positive and GRIK2–negative tumors were 90.2% and 70.1% (P = 0.046), respectively." (PMID 28418868, 2017). "Although GRIK2 is distributed throughout the central nervous system, its physiological significance in cancer stem-like cells has not been determined yet." (PMID 28418868, 2017). "The GRIK2 Q/R, Y/C, and GABRA3 I/M sites emerged as sites with a remarkable editing decrease in GBM (with an editing drop ranging from − 82 to − 74% Δ medians) followed by GLI1 R/G site (− 27% Δ medians), the latter playing a key role in modulating the Hedgehog (HH) signaling in cancer." (PMID 30760294, 2019).
neurodevelopmental disorder (7 papers, 2018 to 2025). A behavioral and cognitive disorder with onset during the developmental period that involves impaired or aberrant development of intellectual, motor, or social functions. "Mutations in GRIK2 underlie various neurodevelopmental disorders." (PMID 40894480, 2025). "For example, the GRIK2 gene may underlie diverse neurodevelopmental disorders." (PMID 38049711, 2023). "In addition, recurrent de novo variants (GRIK2p.Ala657Thr, GRIK2p.Thr660Lys, and GRIK2p.Thr660Arg) in the GRIK2 gene were identified in various neurodevelopmental disorders." (PMID 35629206, 2022).
psychiatric disorder (7 papers, 2009 to 2024). A disorder characterized by behavioral and/or psychological abnormalities, often accompanied by physical symptoms. "We further measured the mRNA levels of a number of genes known to be involved in the pathology of psychiatric disorders, including Bdnf, Fosb, Drd1/2, Grik2, Hdac1/9v, and Grin2a/b." (PMID 36582489, 2022). "Previous studies have shown that the frequencies of RNA editing in GluR2, GRIK2 and 5HT2C receptor were altered in human psychiatric disorders." (PMID 22912834, 2012).
GRIK2 also shares sentences with these, for which no sentence is quoted: neurological diseases (5 papers); Cerebral ischemia (4); prostate carcinoma (4); astrocytoma (3); Parkinson disease (3); alcohol dependence (2); Ataxia (2); Cognitive impairment (2); glioblastoma (2); hepatocellular carcinoma (2); Huntington disease (2); liver cancer (2); melanoma (2); mood disorder (2); ovarian carcinoma (2); panic disorder (2); temporal lobe epilepsy (2); alcoholics (1); Autoimmunity (1); brain disorder (1); cerebellar ataxia (1); Cerebellar atrophy (1); cognitive decline (1); colon cancer (1); congenital night blindness (1); cutaneous T-cell lymphoma (1); diabetes (1); esophageal adenocarcinoma (1); generalized epilepsy (1); glaucoma (1).
A further 18 diseases each share a sentence with GRIK2 in 1 paper.